INS (insulin)
Diseases named in the same sentence as INS in open-access papers (continued):
Sharing a sentence is not in itself a finding about the gene and the disease.
diabetes (continued). "There was no personal or family history of diabetes mellitus or other endocrinopathies, such as insulinoma, or previous use of oral hypoglycemic drugs such as sulfonylureas or exogenous insulin." (PMID 30462811, 2018). "In addition to diabetes-related complications, change in life style, physical well-being, quantity and quality of social relationships, intensive treatment regimen (multiple insulin injections), episodes or fear of hypoglycemia may lead to reduced quality of life (QOL)." (PMID 30382867, 2018). "No recovery of penile cavernosum was observed when insulin treatment started later than 12 weeks after inducing diabetes mellitus in rats." (PMID 30053902, 2018). "Cameron C, Coyle D, Ur E, Klarenbach S. Cost-effectiveness of self-monitoring of blood glucose in patients with type 2 diabetes mellitus managed without insulin." (PMID 29527102, 2018). "The considerable difference in skinfold thickness may partly explain the large between-subject variability in insulin depot size, SBF, and insulin absorption among people with diabetes." (PMID 30116732, 2018). "In diabetes, peripheral cells do not efficiently uptake glucose from the extracellular fluid due to the reduced insulin function." (PMID 30142893, 2018). "Studies with insulin-resistant human subjects showed abnormal ceramide accumulation in vastus lateralis muscle compared to lean subjects with no family history of diabetes." (PMID 30474555, 2018). "The baseline LH concentrations were not related to change in LH concentrations after intranasal insulin in lean mean (r = −0.47, p = 0.35) or in men with diabetes (r = 0.46, p = 0.25)." (PMID 30515210, 2018). "Patients with C peptide-negative diabetes were included in this study in order to ignore metformin effects on beta cell function; metformin correlates with insulin resistance and beta-cell function." (PMID 29338714, 2018). "Management questions that will require more study include the optimal time to start insulin in a patient diagnosed with stage 3 disease without symptoms (“silent diabetes”)." (PMID 29559955, 2018). "The insulin sensitivity estimations were carried out also without subjects with diabetes leading to significantly higher OGIS and Gutt score after the glucose-CPTRO than after glucose-cream, by 16% (p = 0.003) and 22% (p = 0.006), respectively." (PMID 29755591, 2018). "There is a (small) chance that our findings are subject to confounding by indication; severe diabetes and not insulin is related with increased p-mTOR and IGF1R expression." (PMID 29486734, 2018). "Treating hyperglycemia in previously non-diabetic individuals with exogenous insulin immediately after kidney transplantation reduced the odds of developing Posttransplantation Diabetes Mellitus (PTDM) in our previous proof-of-concept clinical trial." (PMID 29518094, 2018). "To better evaluate the effects of insulin treatment during Pb18 infection in diabetic and nondiabetic mice, we first analyzed the characteristic parameters of type 1 diabetes mellitus throughout the experimental period." (PMID 30426021, 2018). "Differences between insulin and metformin strata may also reflect the expected greater effect of SGLT2 inhibitors on mealtime glucose excursions, most prominent in early diabetes." (PMID 30222367, 2018). "Diabetes mellitus (DM) is a metabolic disease in which the body does not produce insulin or cannot use it properly." (PMID 30356347, 2018). "Diabetes is a non-communicable disease with multiple etiological factors resulting from a defect in insulin secretion, insulin action, or both, leads to chronic hyperglycemia with disturbances in the metabolism of carbohydrates, lipids, and proteins." (PMID 30745874, 2018). "Moreover, PP2A mRNA was increased in liver, muscle and adipose tissue derived from insulin resistant Zucker Diabetic Fatty (ZDF) rats, thus suggesting a role for PP2A in the deregulation of insulin signaling in T2D." (PMID 30469501, 2018).
diabetes (continued). "Insulin signaling down-regulation has been related with over activity of protein tyrosine phosphatase 1B (PTP1B) enzyme, which has been a promising target for the treatment of diabetes mellitus." (PMID 29546042, 2018). "More recent studies, such as the DPT-1, have shown that this is not the case, and others looking at intensive insulin therapy initiated shortly after diabetes diagnosis fail to show increased preservation of C-peptide compared to conventional treatment." (PMID 29559955, 2018). "Diabetes—a disease attributable to a disorder of the metabolism—is the result of insufficient hormones (commonly called insulin) secreted by pancreatic β cells or nonfunctioning β cells." (PMID 30309023, 2018). "The original clinical criteria to define MODY included an age of onset below 25 years, not requiring insulin treatment and having a generational family history of diabetes." (PMID 30377832, 2018). "Several studies have been conducted to detect factors associated with insulin adherence worldwide, but none explored the impact of trust in physician and diabetes-related emotional distress on adherence to insulin." (PMID 29520741, 2018). "Patients with gradable images tended to be younger, female, had shorter duration of diabetes, not taking insulin, and had a recorded value for A1c (i.e., not missing data)." (PMID 29924846, 2018). "This study has also confirmed that sensor accuracy is robust to patient characteristics such as age, BMI, insulin versus noninsulin use, diabetes type, and also to the stage of pregnancy." (PMID 29470094, 2018). "Type 2 Diabetes Mellitus (T2DM) is a chronic disease characterized by the inability of the pancreas to produce sufficient amounts of insulin, or when the organism does not use the insulin it produces in an efficient manner." (PMID 30036937, 2018). "Diabetes-specific quality of life was significantly associated with three factors that interacted with each other: diabetes duration, treatment with insulin, and the presence or absence of diabetic retinopathy." (PMID 29530048, 2018). "Although no child was diagnosed with type 2 diabetes mellitus in this study, fastingglycemia and insulin were significantly higher in G1 when compared to G2 (p=0.006and p<0.0001, respectively)." (PMID 30365811, 2018). "Certainly, there are many patients with CVD that require insulin therapy for various reasons: progression of longstanding diabetes; failure to achieve glycemic control by other means (i.e., OAD); or because of comorbidities (i.e., CKD) that make insulin therapy a preferred therapeutic choice." (PMID 29636104, 2018). "Nevertheless, during diabetes the BACE1-dependent cleavage of liver IR, by reducing hepatic insulin sensitivity, may also contribute to peripheral metabolic disorder." (PMID 29610518, 2018). "The RIAS analysis did not include the “ad hoc” consultations that occurred in the diabetes clinic (in which, eg, patients sought an immediate, and often very quick, Skype encounter with a clinician known to them to sort out a problem with insulin dosage)." (PMID 29625956, 2018). "For example, large improvements in insulin resistance occur after exercise and/or caloric restriction in obese adults with and without diabetes." (PMID 29471797, 2018). "Because it was a noninterventional study, insulin therapies were prescribed by diabetologists according to a standard clinical practice and the data gave an insight into the model of diabetes care in real-life setting across Poland." (PMID 29755520, 2018). "By contrast, most patients with diabetes diagnosed in middle age who have islet antibodies do not usually proceed rapidly to insulin therapy." (PMID 29199115, 2018). "Those with DKD comprised 203 (50.1%) of the sample and were likely to be older, male, have a higher total to HDL cholesterol ratio, higher UACR, longer duration of diabetes, higher SBP, greater WHR, and were more likely to be on insulin and have DR (all p < 0.05)." (PMID 30400648, 2018).
diabetes (continued). "The authors noted significant reduction in serum insulin levels without overt diabetes at 30–35 Gy IORT doses." (PMID 30509287, 2018). "One gene was identified in the adipose tissue of gerbils with diabetes: Fabp4, also known as adipocyte FABP (A-FABP) or aP2, which is abundantly expressed in adipocytes and may be a mediator of systemic insulin sensitivity and lipid and glucose metabolism." (PMID 29394254, 2018). "The number of patients needing diabetes medications and/or insulin treatment decreased after surgery and was not different between the LRYGB and the LSG group, neither at baseline nor postoperatively up to 12 months." (PMID 29264780, 2018). "These five patients are insulin-dependent and three had no improvement in their initial poor diabetes response to thiamine." (PMID 29450569, 2018). "One dose of 40 IU of regular insulin administered intranasally does not change LH concentrations acutely in either healthy lean men or in men with diabetes." (PMID 30515210, 2018). "In contrast, high but not low insulin predicted incident diabetes mellitus (115 cases) (HR 1.70, 95% CI 1.08–2.68 and HR 0.76, 95% CI 0.43–1.37, respectively)." (PMID 29997193, 2018). "Diabetes is a complex disease and the classification into Type 1 and Type 2 does not include all metabolic disorders related with impaired insulin secretion or action." (PMID 30346951, 2018). "Type 1 diabetes mellitus, the most prevalent form of diabetes in childhood, was ruled out in cases 4–9 as there was no ketosis without insulin therapy and pancreatic autoantibodies were negative." (PMID 29510678, 2018). "This is consistent with genome-wide association studies (GWAS) that have found genetic drivers of diabetes that effect insulin production but not insulin resistance." (PMID 29444133, 2018). "Diabetes mellitus is one of the most common chronic metabolic disease due to lack of insulin (INS) (T1DM) or INS resistance (T2DM)." (PMID 29226733, 2018). "This study showed improved clinical outcomes to treatment with everolimus and octreotide in patients that were also treated with metformin for diabetes as compared with patients that were treated with insulin or as compared with nondiabetic patients." (PMID 28616837, 2018). "Compared with age-matched women without diabetes, insulin-treated T1D patients had greater percent dense (8.7% vs. 11.4%) and absolute dense volumes (59.7 vs. 64.7 cm3), and a smaller absolute nondense volume (615 vs. 491 cm3)." (PMID 30092829, 2018). "Further, more than half of the pre-DP diabetes patients without the use of insulin had deterioration of glucose metabolism after DP." (PMID 29541399, 2018). "In contrast to previous studies in the setting of diabetes mellitus and infectious disease, the amount of insulin given and the acquisition of a new infection were not independently associated with telomere shortening in our study." (PMID 29463275, 2018). "Diabetes is a chronic disease that occurs when the endocrine cells of the pancreas do not produce enough insulin, or when the organism is unable to properly use insulin to regulate blood sugar concentration." (PMID 29552330, 2018). "Insulin pumps and continuous glucose monitors (CGM) are advanced diabetes management devices that may lead to improved glycemic control compared to traditional insulin injections with self-monitoring of blood glucose (SMBG)." (PMID 30151393, 2018). "In contrast, in patients with type 2 diabetes mellitus (T2DM), endogenous insulin secretion may be insufficient to maintain glucose homeostasis during additional, stress-induced insulin resistance as occurs during critical illness." (PMID 28497374, 2017). "Diabetes developed between 11 and 18 years, was non-autoimmune and insulin requiring even if some residual endogenous insulin secretion was present." (PMID 28951826, 2017). "The treatment of diabetes requested in the lawsuits studied has no scientific basis justifying the non-use of the insulin prescribed in the SUS." (PMID 28724420, 2017).
diabetes (continued). "Patients who used insulin presented a time of evolution of diabetes of 18.37±9.01 years while those who did not use insulin presented a time of evolution of 13.53±9.4 years (T-test, p = 0.007)." (PMID 28767676, 2017). "These glycemic levels in the DM group are consistent with a type 1 diabetes mellitus scenario without insulin replacement." (PMID 28676554, 2017). "Among those subjects not affected by diabetes mellitus, insulin levels tended to be lower in the AG+GG group (4.8 vs 5.7 μU/ml, age-sex-BMI adjusted p = 0.04)." (PMID 29253899, 2017). "Risk for discontinuation was 20% lower in non‐smokers and patients who used other glucose‐lowering medicines than insulin compared with smokers and patients who did not fill any prescriptions for diabetes medicines (the references) (P < 0.0001)." (PMID 28799214, 2017). "During diabetes, glycosylated hemoglobin is formed progressively and irreversibly over a period of time and is stable till the life of the RBC and is unaffected by diet, insulin or exercise on the day of testing." (PMID 28077129, 2017). "Since patients under 8 years of age were not included, the subjects of this study had diagnosed diabetes for a longer period, had higher BMI, were more frequently insulin pump users and were slightly older than the total population of youth with T1D in Norway." (PMID 28683835, 2017). "Unfortunately, reliable statistics on proportion of diabetes patients using insulin are lacking from Nepal." (PMID 29333459, 2017). "Our study also revealed that there is increased usage of insulin in microalbuminuric group as compare to those who have no microalbuminuria, it signifies that their diabetes were difficult to control on oral hypoglycemics only." (PMID 28811763, 2017). "type 2 diabetes mellitus (T2DM), the seventh cause of worldwide mortality is a complex disorder resulting from the absolute or relative lack of insulin." (PMID 29988211, 2017). "In 15 men with hemochromatosis, phlebotomy therapy lowered insulin requirements in those with insulin dependency and improved diabetes control in about half of those without insulin dependency." (PMID 28331855, 2017). "After adjusting for age, sex, and significant clinical variables such as BMI, duration of diabetes, SBP, pulse pressure, heart rate, smoking, alcohol consumption, HbA1c, HDL cholesterol, hsCRP, insulin treatment, and RAS inhibitors, baPWV was significantly correlated with the ACR (models 2 and 3)." (PMID 28951879, 2017). "Second, we employed an animal model of type-1 diabetes and we studied only short term effects of diabetes and without insulin treatment." (PMID 28727746, 2017). "Lower average and promoter DNA methylation of SLC22A1, SLC22A3, and SLC47A1 was found in diabetic subjects receiving just metformin, compared to those who took insulin plus metformin or no diabetes medication." (PMID 28947922, 2017). "Intensity of insulin treatment influences weight gain as shown in the Diabetes Control and Complications Trial (DCCT), where patients on intensive insulin therapy gained an average of 4.6 kg over 5 years, which is significantly more than patients in the study’s conventional arm." (PMID 28836234, 2017). "Recombinant human insulin introduced as a basic treatment for patients suffering from diabetes in the 1980s did not, however, mimic the physiological profile of endogenous hormone release." (PMID 28296883, 2017). "For example If all other cost assumptions are kept as established for S1 and S2, and the cost of insulin is reduced to US$ 4.20 per vial, it would result in cutting direct cost in 50% and the per capita cost of diabetes care by 35% (data not shown)." (PMID 29163935, 2017). "We performed explorative analyses separately in type 1 and type 2 insulin-treated premenopausal women with diabetes trying to understand these differences between insulin and non-insulin users." (PMID 28076434, 2017).
diabetes (continued). "Quercetin, a strong antioxidant flavonoid revealed a protective effect against STZ-induced diabetes in rats by intraperitoneal injection of quercetin 15 mg/kg BW for 3 days prior to STZ administration and protected an insulin secreting cell line (INS-1) against oxidative damage." (PMID 28336764, 2017). "First-line medications for diabetes management were available in the majority of public facilities, although sulphonylureas and insulin were lacking in Shimla public hospitals." (PMID 29282052, 2017). "Additionally, those individuals attending specialist diabetes services were more likely: to have received diabetes education recently; to be knowledgeable about HbA1c; to have carried out SMBG; and to be injecting insulin more than twice daily." (PMID 28489876, 2017). "Several variables influence the glucose metabolism among diabetic population, including weight status, gender, age and type of diabetes (insulin dependent versus non-insulin dependent)." (PMID 28770010, 2017). "When insulin resistance reaches this severe stage, pancreatic beta cells no longer produce enough insulin to overcome the lack of insulin signaling, and blood glucose levels rise ultimately resulting in diabetes." (PMID 28070499, 2017). "It was also shown that deficiency of Leptin-receptor in zebrafish leads to elevated insulin levels after feeding and a diabetes-like defect in wound healing, although it does not lead to elevated blood glucose levels and obesity in animals." (PMID 28925940, 2017). "Consistent with previous studies, without carbohydrates NZO mice become obese and insulin-resistant, but are protected from developing diabetes." (PMID 28770320, 2017). "Although conventional insulin sensitizers, including metformin and rosiglitazone, have been proven to improve insulin sensitivity in target tissues, no pharmacologic agents exist which can be proven to treat diabetes completely." (PMID 29096724, 2017). "In animals with diabetes induced by streptozotocin and nicotinamide, resveratrol supplementation increased the VAMP2 gene expression and blood insulin level, as well as reduced the fasting blood glucose and improved the insulin resistance." (PMID 28812028, 2017). "There are two forms of diabetes mellitus: type I, when the pancreas does not produce enough insulin, and type II, when the body cannot effectively use the produced insulin." (PMID 28758130, 2017). "Type 2 diabetes mellitus (T2DM), a disease on the rise and with huge economic burden to health care systems around the globe, results from defects in insulin action (termed insulin resistance) combined with impaired insulin secretion." (PMID 28862678, 2017). "The trajectory of fasting insulin in adults who did not develop diabetes was significantly lower than that in adults who developed diabetes, when examined according to low, medium, and high BMI groups, respectively (all P < 0.001)." (PMID 28266592, 2017). "Youth with T1DM tends to exercise less than youth without diabetes, most likely due to fear of hypoglycemia due to insulin [44••, 60]." (PMID 29101482, 2017). "Twenty-five percent (n = 53) of the women with diabetes were treated with insulin; including 18 combined with non-insulin antidiabetic drugs." (PMID 28076434, 2017). "While ZnT8 plays a critical role in insulin physiology, and over the last decade or so this transporter has been given much attention for its role in diabetes, other zinc transporters have not had the same focused attention until recently." (PMID 29157234, 2017). "It has also been observed that the time elapsed since diagnosis of diabetes was higher among insulin-dependent patients compared to non-insulin-dependent patients, with a mean of 18.37±9.01 years and 13.53± 9.4 years, respectively (p = 0.007)." (PMID 28767676, 2017).